RARS2 (arginyl-tRNA synthetase 2, mitochondrial)
Description:
Catalyzes the attachment of arginine to tRNA(Arg) in a two-step reaction: arginine is first activated by ATP to form Arg-AMP and then transferred to the acceptor end of tRNA(Arg).
Synonyms: ArgRS; RARSL; MGC14993; MGC23778; PRO1992; dJ382I10.6; DALRD2; PCH6
Tractability: PROTAC: ubiquitination databases record sites on it; its protein half-life has been measured.
Target class: Enzyme; Ligase
Gene: Protein-coding gene on chromosome 6 (87,513,459 to 87,590,028, reverse strand). Ensembl gene ENSG00000146282.
Subcellular location: Mitochondrion membrane
Subcellular location (Human Protein Atlas): Mitochondria
Pathways (Reactome):
Metabolism of proteins: Mitochondrial tRNA aminoacylation
Gene Ontology:
Molecular function: arginine-tRNA ligase activity; protein binding; RNA binding; aminoacyl-tRNA ligase activity; ATP binding; nucleotide binding
Biological process: mitochondrial translation; tRNA aminoacylation for protein translation; arginyl-tRNA aminoacylation; gene expression; tRNA metabolic process
Cellular component: mitochondrial membrane; mitochondrion; mitochondrial matrix; cytoplasm
Genetic constraint (gnomAD): Loss-of-function variants: 51 observed, 72.72 expected, observed/expected ratio (o/e) 0.7, 90% interval 0.56 to 0.89. The upper end of that interval is the gene's LOEUF score, 0.89, which puts it in group 3 of 6, group 1 being the genes least tolerant of losing a copy. Missense variants: 592 observed, 627.26 expected, observed/expected ratio (o/e) 0.94, 90% interval 0.88 to 1.01. Synonymous variants: 213 observed, 212.82 expected, observed/expected ratio (o/e) 1, 90% interval 0.89 to 1.12.
Gene-disease validity (ClinGen):
ClinGen rates the evidence that RARS2 causes each of these diseases.
mitochondrial disease (autosomal recessive): Definitive.
Homologues: Orthologues: macaque RARS2 (98% identical), chimpanzee RARS2 (98% identical), dog RARS2 (93% identical), pig RARS2 (93% identical), rabbit RARS2 (92% identical), guinea pig RARS2 (90% identical), mouse Rars2 (87% identical), rat Rars2 (86% identical), tropical clawed frog rars2 (63% identical), zebrafish rars2 (57% identical), Drosophila melanogaster ArgRS-m (35% identical). Paralogues in human: RARS1 (28% identical).
Diseases named in the same sentence as RARS2 in open-access papers:
RARS2 is named in the same sentence as 48 diseases in open-access papers, as found by Europe PMC text mining. Sharing a sentence is not in itself a finding about the gene and the disease. The quoted sentences say what the papers report.
pontocerebellar hypoplasia type 6 (14 papers, 2014 to 2025). Pontocerebellar hypoplasia type 6 (PCH6) is a rare form of pontocerebellar hypoplasia characterized clinically at birth by hypotonia, clonus, epilepsy impaired swallowing and from infancy by progressive microencephaly, spasticity and lactic acidosis. "Pontocerebellar hypoplasia type 6 (PCH6) is a recessive genetic disorder caused by a mutation in the RARS2 gene (MIM611524)." (PMID 40182349, 2025). "His exome sequencing revealed a previously reported homozygous likely pathogenic variant in the RARS2 gene (NM_020320.5:c.1026G > A;p.(Met342Ile)) causing the mitochondrial-encephalopathy disorder pontocerebellar hypoplasia, type 6 (OMIM# 611523)." (PMID 39551846, 2024). "Biallelic variants in the RARS2 gene are reported to cause a mitochondrial encephalopathy (Pontocerebellar hypoplasia, type 6 (PCH 6); OMIM# 611523)." (PMID 39551846, 2024). "RARS2 was an identified cause of pontocerebellar hypoplasia type 6 with autosomal recessive inheritance, typically characterized by pontine atrophy, vermian hypoplasia, infantile encephalopathy, generalized hypotonia, and intractable seizures." (PMID 33897753, 2021). "Patients with RARS2 mutations exhibit early onset hypotonia, epileptic seizures, encephalopathy, and feeding difficulties in a syndrome termed pontocerebellar hypoplasia type 6 (PCH6)." (PMID 33115496, 2020). "Mutations within RARS2, the gene coding for the mitochondrial arginyl-tRNA synthetase (mt-ArgRS), are correlated with pontocerebellar hypoplasia type 6 (PCH6)." (PMID 30006346, 2018). "Pontocerebellar hypoplasia type 6 (PCH6) is a mitochondrial disease caused by mutations in the RARS2 gene." (PMID 27769281, 2016). "We describe a family of two affected boys with pontocerebellar hypoplasia type 6 and mutations in RARS2, presenting with infantile spasms." (PMID 27061686, 2016). "Mutations in RARS2 cause a neurodegenerative disorder, pontocerebellar hypoplasia type 6." (PMID 28355232, 2017). "RARS2 causes pontocerebellar hypoplasia type 6 (PCH6), which is characterized by an abnormally small cerebellum and brainstem and associated with severe developmental delays." (PMID 35571021, 2022). "Pontocerebellar hypoplasia type 6 (PCH6) is a mitochondrial disease with autosomal recessive inheritance caused by mutations in the RARS2 gene." (PMID 27769281, 2016). "Mutations in RARS2 have been reported in patients with pontocerebellar hypoplasia type 6 (PCH6, OMIM 611523).2, 6, 7, 8, 9, 10, 11, 12 The gene encodes the mitochondrial aminoacyl‐tRNA synthetase (ARS) enzyme, arginyl transfer RNA synthetase (MIM 611524)." (PMID 27061686, 2016).
epilepsy (8 papers, 2016 to 2025). A brain disorder characterized by episodes of abnormally increased neuronal discharge resulting in transient episodes of sensory or motor neurological dysfunction, or psychic dysfunction. "In RARS2 deficiency, four patients with epilepsy were treated with arginine (150–350 mg/kg, twice daily)." (PMID 41404429, 2025). "These patients also had poorly characterized baseline phenotypes but were described as harboring epilepsy, which is usually severe and debilitating in RARS2-associated disease." (PMID 41404429, 2025). "Here, we describe two unrelated patients with a novel RARS2 phenotype and reanalyse the published RARS2 epilepsy phenotypes and variants." (PMID 34717047, 2022). "In conclusion, we report two patients with RARS2 mutations in the context of severe neurodevelopmental delay, an intractable seizure disorder and abnormal MRI brain scan." (PMID 27061686, 2016). "Some patients may only have nervous system abnormalities or epilepsy as the main manifestation; however, patients previously reported with epilepsy bearing variants in RARS2 and SURF1 are rare." (PMID 34992632, 2021). "In the 15 published cases that describe the RARS2 epilepsy phenotype in detail, seizure onset occurred by 3 months in the setting of abnormal development." (PMID 34717047, 2022).
Encephalopathy (7 papers, 2014 to 2024). Encephalopathy is a term that means brain disease, damage, or malfunction. "The patient homozygous for the RARS2 variant (c.392T>G, p.F131C) presented with severe encephalopathy, intractable seizures, and profound developmental delay." (PMID 37975900, 2024). "Clinical spectrum of RARS2 mutations typically include neurological symptoms such as encephalopathy with intractable seizures and severe developmental delay, primarily affecting the brain." (PMID 39624497, 2024). "Through the identification of this additional case, this study validates the homozygous RARS2 variant NM_020320.3:c.-2A- > G as the molecular cause for this severe encephalopathy." (PMID 37344844, 2023). "The first patients with splice-site mutation in either DARS2 or RARS2 presented with encephalopathy." (PMID 24639874, 2014). "Overall, our bioinformatic reanalysis suggests that 85% of the now 52 RARS2 variants likely impact on splicing or expression of the gene and that most cases with RARS2 encephalopathy have at least one variant with this effect (46/54 with two variants, 7/54 with one variant)." (PMID 34717047, 2022). "Bi-allelic variants in the mitochondrial arginyl-transfer RNA synthetase (RARS2) gene have been involved in early-onset encephalopathies classified as pontocerebellar hypoplasia (PCH) type 6 and in epileptic encephalopathy." (PMID 37344844, 2023).
Epileptic encephalopathy (7 papers, 2018 to 2024). A condition in which epileptiform abnormalities are believed to contribute to the progressive disturbance in cerebral function. "The variants were re-classified as causative after the observation of the missense change in two other unrelated patients with early onset epileptic encephalopathy and several reports of patients with RARS2 mutations and intact cerebellum." (PMID 30091983, 2018). "We describe a new RARS2 phenotype of infantile‐onset myoclonic developmental and epileptic encephalopathy in two unrelated children and compare this to the epileptology in the previously reported cases." (PMID 34717047, 2022). "Subsequently, a recessive RARS2 early‐infantile (<12 weeks) developmental and epileptic encephalopathy was described with hypoglycaemia and lactic acidosis." (PMID 34717047, 2022). "There are two main overlapping clinical conditions associated with biallelic pathogenic RARS2 variants: (i) PCH6 that was initially described and (ii) early onset epileptic encephalopathy without typical PCH on MRI." (PMID 37344844, 2023).
pontocerebellar hypoplasia (7 papers, 2014 to 2025). Pontocerebellar hypoplasias (PCH) are a rare heterogeneous group of diseases characterized by hypoplasia and atrophy and/or early neurodegeneration of the cerebellum and pons. "For example, the lethal heterogeneous neurodegenerative disease pontocerebellar hypoplasia (PCH6) was linked to the RARS2 (mitochondrial arginyl-tRNA synthetase) gene in a patient with a homozygous frameshift mutation predicted to generate a truncated protein." (PMID 24917879, 2014). "In a cohort of 169 cases of pontocerebellar hypoplasia, 106 were linked to mutations in four genes (TSEN54, TSEN2, TSEN34 and RARS2)." (PMID 28549128, 2017).
Mitochondrial encephalopathy (5 papers, 2018 to 2025). "Interestingly, the reclassification of the RARS2-associated phenotype as an early onset mitochondrial encephalopathy was further supported by elevated lactate levels in cerebrospinal fluid observed in our patient, as well as a lactate peak on her MR-spectroscopy." (PMID 30091983, 2018).
developmental delay (4 papers, 2018 to 2025). "These diseases display a broad clinical spectrum and may be further complicated with other symptoms such as developmental delay (NARS2, PARS2), pontocerebellar hypoplasia (RARS2), visual impairment (FARS2) psychomotor delay (TARS2) and microcephaly (VARS2)." (PMID 29288497, 2018).
lactic acidosis (4 papers, 2016 to 2024). Metabolic acidosis characterized by the accumulation of lactate in the body. "The earliest abnormality in patients with RARS2 mutations is usually lactic acidosis due to impairment of the respiratory chain." (PMID 27769281, 2016).
Infantile encephalopathy (3 papers, 2014 to 2022). Encephalopathy with onset in the infantile period. "We expand the RARS2 phenotypic spectrum to include infantile encephalopathy and suggest this gene is enriched for pathogenic variants that disrupt splicing." (PMID 34717047, 2022). "Pontocerebellar hypoplasia 6, a severe infantile encephalopathy with cerebral atrophy and multiple OXPHOS deficiency, is associated with RARS2 (MIM# 611524) (mitochondrial arginyl-tRNA synthetase) mutations." (PMID 24827421, 2014).
Cerebral atrophy (2 papers, 2014 to 2016). Atrophy (wasting, decrease in size of cells or tissue) affecting the cerebrum. "From a radiologic perspective, RARS2‐PCH is associated with cerebral atrophy and pontocerebellar hypoplasia/atrophy." (PMID 27061686, 2016).
infantile spasms (2 papers, 2016 to 2018). A rare epilepsy syndrome characterized by onset of epileptic spasms in infants between 2 and 12 months of age, and rarely up to 24 months. "Our data suggest RARS2 should be considered in patients with infantile spasms if other PCH features, such as imaging findings, are present." (PMID 27061686, 2016).
Leber hereditary optic neuropathy (1 paper, 2017). Leber's hereditary optic neuropathy (LHON) is a mitochondrial neurodegenerative disease affecting the optic nerve and often characterized by sudden vision loss in young adult carriers. "For example, EPI-743 (α-tocotrienol quinone) is an investigational drug that is currently in clinical trials focusing on treatment of mitochondrial dysfunction related to primary genetic mitochondrial disease, including Leigh syndrome, Leber Hereditary Optic Neuropathy (LHON), and RARS2 deficiency." (PMID 28467362, 2017).
Perrault syndrome (1 paper, 2014). Perrault syndrome (PS) is characterized by the association of ovarian dysgenesis in females with sensorineural hearing impairment. "Interestingly, hearing problems are present also in patients with PCH6 (due to RARS2 mutations) or Perrault syndrome (caused by LARS2 or HARS2 mutations)." (PMID 24639874, 2014).
Pontocerebellar atrophy (1 paper, 2016). Atrophy affecting the pons and the cerebellum. "Our cases demonstrate that the characteristic neuroradiological abnormalities of PCH6 such as vermis and cerebellar hypoplasia and progressive pontocerebellar atrophy may be missing in some individuals, further expanding the spectrum of RARS2 mutations." (PMID 27769281, 2016). "Characteristic neuroradiological abnormalities of PCH6 such as vermis and cerebellar hypoplasia and progressive pontocerebellar atrophy may be missing in patients with RARS2 mutations." (PMID 27769281, 2016).
mitochondrial disease (3 papers, 2016 to 2023). "PCH6 is usually considered as a mitochondrial disease due to variants in the gene encoding for mitochondrial arginyl-transfer RNA (tRNA) synthetase (RARS2)." (PMID 37344844, 2023).
neurological disease (2 papers, 2018 to 2022). "We speculate that in RARS2, these low levels do not reach the threshold for sufficient mitochondrial function and result in the progressive neurological disease." (PMID 34717047, 2022).
tumor (2 papers, 2010 to 2020). "Remarkably, specific aaRS genes do show a DNA profile reminiscent of an oncogene (e.g., GARS1, AIMP2, and YARS2) or tumor suppressor (e.g., NARS1, QARS1, LARS2, and RARS2)." (PMID 33266490, 2020).
cancer (1 paper, 2020). A tumor composed of atypical neoplastic, often pleomorphic cells that invade other tissues. "Loss-of-function mutations in RARS2 have been linked to severe multi-system disorders but not yet to cancer." (PMID 33266490, 2020). "There are a few aaRSs that are downregulated in multiple cancer types, including HARS2 (n = 6), WARS1 (n = 4), CARS2 (n = 4), IARS1 (n = 3), RARS2 (n = 3), VARS2 (n = 3), and AIMP3/EEF1E1 (n = 3), suggesting these aaRSs may possess certain specific cancer-inhibiting roles." (PMID 33266490, 2020).
cardiovascular disease (1 paper, 2017). "Particulate air pollution is known to cause mitochondrial damage which can lead to cardiovascular disease, making RARS2 an interesting candidate gene for further analyses." (PMID 28355232, 2017).
metabolic disease (1 paper, 2025). A congenital disorder (due to inherited enzyme abnormality) or acquired (due to failure of a metabolically important organ) disorder resulting from an abnormal metabolic process. "Notably, movement disorders are often associated with metabolic diseases and have been described in conditions related to deficiencies in other aminoacyl-tRNA synthetases, including WARS2, CARS2, PARS2, RARS2, and AARS2." (PMID 41002930, 2025).
RARS2 also shares sentences with these, for which no sentence is quoted: Ataxia (2 papers); genetic disorder (2); Intellectual disability (2); Leigh syndrome (2); microcephaly (2); Rett syndrome (2); Alpers syndrome (1); Atrophy (1); Autosomal recessive spastic ataxia with leukoencephalopathy (1); Brain atrophy (1); breast tumors (1); epilepsy syndrome (1); epileptic seizures (1); Hypertonia (1); hypoglycaemia (1); Hypotonia (1); infection (1); leukodystrophies (1); Leukoencephalopathy (1); movement disorder (1); neurodegenerative disease (1); Neurodevelopmental delay (1); ovarian failure (1); OXPHOS disease (1); progressive ataxia (1); sensorineural hearing loss with (1); Tremor (1); viral infection (1).